PRMT1 (protein arginine methyltransferase 1)
Diseases named in the same sentence as PRMT1 in open-access papers (continued):
Sharing a sentence is not in itself a finding about the gene and the disease.
tumor (continued). "PRMT1 expression was positively correlated with DNA replication and negatively correlated with apoptosis pathways in TNBC, highlighting its potential role in promoting tumor cell survival and proliferation." (PMID 40927753, 2025). "PRMT1 knockdown significantly suppressed tumor growth and enhanced CBP's anti‐tumor effect." (PMID 40270464, 2025). "Additionally, combined inhibition of PRMT1 and STING expression in GC resulted in a slight recovery of tumor growth." (PMID 40858547, 2025). "For example, dual targeting of PRMT1 and PRMT5 has produced synergistic inhibition of tumor growth." (PMID 40791817, 2025). "Similarly, in laryngeal cancer, PRMT1 modulates nuclear receptor coactivator 5 (NCOA5) expression via H4R3me2a, facilitating tumor cell proliferation, migration, and invasion." (PMID 41256732, 2025). "PRMT1 also methylates RIP3 at arginine 486, thereby inhibiting the interaction between RIP3 and RIP1, which suppresses necrosome formation and downstream necroptotic signaling, eventually limiting tumor immune evasion." (PMID 41256732, 2025). "PRMT1 significantly contributes to chemoresistance in TNBC by altering the methylation of key molecules like epidermal growth factor receptor (EGFR) and phosphoglycerate dehydrogenase (PHGDH), which strengthens tumor resilience." (PMID 40927753, 2025). "Multivariate Cox regression models confirmed that circ-PRMT1 is an independent prognostic factor for survival outcomes, irrespective of tumor location, histological grade, TNM stage, or therapy." (PMID 40724932, 2025). "Collectively, we propose that PRMT1 oligomerization, rather than mere dimerization, is sufficient for PRMT1-driven PDAC tumor growth, offering novel insights into the potential therapeutic targeting of PRMT1 oligomeric forms in PDAC." (PMID 40675804, 2025). "The reintroduction of PRMT1 oligomers, but not dimers or monomers, reversed tumor growth inhibition." (PMID 40675804, 2025). "FAM98A has been reported as a substrate of protein arginine methyltransferase 1 (PRMT1) and may be involved in tumor cell migration and invasion." (PMID 39857276, 2025). "Given the potential role of PRMT1 in antitumor immunity and the significant effect of the TME on GC progression, we established this study to explore the specific role of GC-derived PRMT1 and its downstream effects in tumor immune microenvironment." (PMID 40858547, 2025). "For example, if an inhibitor targeting PRMT1 also inhibits PRMT5, it could disrupt normal immune responses or cell cycle control, which not only weakens the anti‐tumour effect but might also lead to serious side effects in patients." (PMID 39964832, 2025). "In HCC, PRMT1 methylates PFKFB3, promoting glycolysis and tumor progression." (PMID 41204384, 2025). "Our Western blot results support the conclusion that the observed phenotype rescue, where WT oligomeric PRMT1—rather than dimeric or monomeric forms—promotes PDAC tumor growth, is dependent on PRMT1’s catalytic activity." (PMID 40675804, 2025). "Interestingly, protein arginine methyltransferase 1 (PRMT1) is identified as a negative regulator of MHC‐I expression, attenuating CD8+ T cell‐mediated anti‐tumour responses by suppressing IFN‐γ‐induced STAT1 activation." (PMID 40673641, 2025). "In addition, the gene expression level of PRMT1 and USP7 in several tumor types was analyzed by TIMER2.0 network tool." (PMID 39009589, 2024). "Moreover, immunohistochemical (IHC) staining revealed that tumor tissues with FBXO7 KD exhibited increased levels of PRMT1 protein and PHGDH R236 methylation, which was largely restored by PRMT1 KD." (PMID 38839752, 2024). "PRMT1‐depletion inhibited HCC cell proliferation and tumor growth." (PMID 39367565, 2024). "Importantly, the PRMT1 inhibitor GSK3368715 has entered phase I clinical trials, and its main tumor types include pancreatic cancer, non-small cell lung cancer, bladder tumors, and blood tumors of diffuse large B-cell lymphoma." (PMID 38911125, 2024).
tumor (continued). "Increased PRMT1 levels drive the methylation of phosphofructokinase/fructose bisphosphatase type-3 (PFKFB3), leading to enhanced glycolysis, proliferation, migration, and invasion of tumor cells." (PMID 38997696, 2024). "Moreover, PRMT1-mediated methylation of ME2 inhibits ME2-FBW7 interaction and ubiquitination-mediated degradation, promoting tumor cell survival and proliferation." (PMID 39528487, 2024). "The inhibition effect of FLAG-FBXO7 on tumor growth was markedly recovered by the K37R mutant of PRMT1, but not wild-type PRMT1." (PMID 38839752, 2024). "Indeed, the bio-available Prmt1 inhibitors AMI-40858,59 and TC-E 5003 achieved a 50–60% reduction in tumor burden accompanied by a decrease in Ki67+ proliferative cells after 2 weeks of treatment in a syngeneic orthotopic model of PDAC." (PMID 37673892, 2023). "Our defined PRMT1-cGAS signaling axis might partially explain the synergistic effect of inhibition of PRMT1 and PRMT540, in which both the parallel cGAS and IFI16 signaling might be activated to maximal downstream cascade to trigger anti-tumor immunity." (PMID 37193698, 2023). "Overexpression of p120-catenin and PRMT-1 was found in tumor samples recovered from smokers as compared to non-smokers." (PMID 37444572, 2023). "Finally, we compared the responsiveness for the combination treatment of PRMT1 inhibitor and anti-PD-1 antibody between CT26-cGAS-WT and CT26-cGAS-KO syngeneic tumor models." (PMID 37193698, 2023). "Notably, PRMT1, PRMT2, PRMT3, and PRMT7 exhibited upregulation, while PRMT5, PRMT6, and PRMT8 displayed downregulation in tumor." (PMID 37781030, 2023). "In this study, PRMT1, PRMT2, PRMT5, and PRMT8 were significantly highly expressed in After Tumor." (PMID 38136558, 2023). "Interestingly, the expression levels of MYC-target genes were significantly reduced after genetic and pharmaceutical ablation of PRMT1, which was consistent with previous reports depicting MYC as a suppressor of anti-tumor immunity." (PMID 37193698, 2023). "Thus, we treated CT26- and MC38-derived syngeneic tumor models with either PRMT1 inhibitor MS023, or anti-PD-1 antibody, or their combination and monitored tumor growth and mouse survival for up to 90 days." (PMID 37193698, 2023). "To further determine whether PRMT1-mediated change in PD-L1 expression is cGAS-dependent, we depleted endogenous cGAS in CT26, MC38, and 4T1 mouse tumor cells, and found a significant reduction in mPD-L1 expression in these cells." (PMID 37193698, 2023). "Similarly, PRMT1 methylation of BRCA1 impacts its capacity to interact with specific partners (e.g., STAT1), and as a result, its tumor-suppressive action is severely affected." (PMID 35885916, 2022). "However, circ-PRMT1-7 was found in the BT-20 and MCF-7 cell lines, even though these cell lines differ in many aspects (histology, molecular subtype, tumor source)." (PMID 35885916, 2022). "Because PRMT1-mediated HBP1 methylation can promote metastasis and growth of tumor cells, we next asked if pharmacological inhibition of HBP1 methylation could suppress tumor cell metastasis and growth." (PMID 35941115, 2022). "PRMT1 expression was lower in both EMT6 and 4T1 tumor cells compared to the normal-like HC11 cells." (PMID 36376929, 2022). "This study identified and characterized PRMT1-dependent regulation of RNA metabolism and coordination of key cellular processes required for PDAC tumor growth, defining a mechanism-based translational hypothesis for PRMT1 inhibitors." (PMID 34330913, 2021). "In summary, we demonstrated that PRMT1-mediated asymmetric dimethylation of NONO at R251 promotes CRC progression by enhancing tumor cell proliferation, migration, and invasion." (PMID 33420374, 2021). "Indeed, recent studies have demonstrated a redundancy between PRMT1 and PRMT5 pathways and synergistic anti-tumor effects of combined inhibition of both PRMTs23–25." (PMID 32415090, 2020).
tumor (continued). "Another possibility to explain the role of PRMT1 in various RCT emerge from the previous suggestions that PRMT1 indirectly, through different transcription factors, may affect tumor cell growth or cell apoptosis." (PMID 31655611, 2019). "In two cases of ccRCC with the highest grade, stage and with the largest tumor dimension relative mRNA PRMT1 expression was the lowest and PRMT1 IHC expression was homogenous negative and heterogenous." (PMID 31655611, 2019). "Furthermore, stable expression of PRMT1 in isolated OV6+ ESCC cells promoted stem cell-like properties, tumour development and chemoresistance." (PMID 31043582, 2019). "Moreover, PRMT1 was identified as a component in the C/EBPα complex, and methylation of C/EBPα inhibited the interaction between C/EBPα and corepressor HDAC3, leading to the activation of cyclin D1 expression and rapid tumor cell growth." (PMID 40001488, 2025). "Despite the challenges in developing PRMT1‐targeted therapies, combination strategies employing PRMT1 inhibitors with PARP inhibitors (PARPis) or immunotherapeutic agents demonstrate considerable potential to overcome drug resistance and remodel the tumor microenvironment." (PMID 41256732, 2025). "Thus, disrupting this pathway by PRMT1 inhibition may lead to HCC cell cycle arrest and a decrease in tumor size." (PMID 40001488, 2025). "Similarly, PRMT1 can suppress the cGAS–STING‐I type interferon pathway in GC, impede M1 macrophage polarization and CD8+ T cell recruitment triggered by dsDNA, and preserve the “cold tumor” phenotype." (PMID 41256732, 2025). "Mechanistically, PRMT1 recruits the SWI/SNF chromatin remodeling complex via direct interaction with SMARCC1, leading to the transcriptional activation of insulin‐like growth factor 2 mRNA‐binding protein 2 (IGF2BP2), which enhances CBP resistance and tumor growth." (PMID 40270464, 2025). "Additionally, PRMT1 inhibition led to a significant downregulation of genes involved in cell proliferation, DNA replication, and DNA damage response (DDR), likely inducing genomic instability and impairing tumor growth." (PMID 41188812, 2025). "However, PRMT1 methylation does not solely impact tumor suppressing transcription factors, but also oncogenic transcription factors like c-Jun." (PMID 40001488, 2025). "In addition, PRMT1 knockdown led to changes in the STAT signaling pathway in the GC TME, invasive M1-like TAM polarization, an enhanced antitumor immune response, and inhibited tumor progression in GC." (PMID 40858547, 2025). "However, the specific role of PRMT1 in the GC tumor immune microenvironment (TME) has not been reported." (PMID 40858547, 2025). "Furthermore, we established that FOSL1 positively regulates global m6A methyltransferase activity in a PRMT1-dependent manner, influencing the expression and function of key RNA methyltransferase METTL3 and its target transcripts involved in DDR and tumor progression." (PMID 41423530, 2025). "Protein arginine methyltransferase 1(PRMT1) enhances CRC proliferation by asymmetrically dimethylating the non-POU domain-containing octamer-binding protein (NONO) at R251, facilitating epidermal growth factor receptor (EGFR) signaling activation and tumor progression." (PMID 40951358, 2025). "For instance, CRC, PRMT1‐mediated methylation of metabolic enzymes like PGK1 and phosphoglycerate dehydrogenase (PHGDH) enhances glycolysis and serine synthesis, promotes the Warburg effect, and increases tumor stemness, thereby fostering a stress‐adaptive state conducive to resistance." (PMID 41256732, 2025). "PRMT1 acts as a suppressor of tumor immune surveillance in a cGAS (cyclic GMP-AMP synthase)-dependent manner through methylating cGAS at the conserved R133 residue on its N-terminus, and then blocking cGAS DNA sensing signaling, thus promoting tumor immune evasion." (PMID 39201539, 2024).
tumor (continued). "In this work, for the first time, we investigated the mechanism of ME2 methylation and observed that PRMT1 mediates the methylation of ME2 and prevents its ubiquitination, which increases its protein stability and enhances mitochondrial respiration and HCC tumor development." (PMID 39528487, 2024). "Our experiments revealed that two PRMT1-specific inhibitors (AMI-1 and MS023) could decrease HBP1 methylation and increase HBP1 protein levels, thereby enhancing HBP1-mediated suppression of tumor growth and metastasis." (PMID 35941115, 2022). "Notably, PRMT1 expression correlated with increased tumor size and higher grade, but not with lymph node status or TNM stage." (PMID 33853662, 2021). "Given that PRMT1 was overexpressed in CRC tissue and PRMT1-mediated arginine methylation of NONO enhanced tumor growth and metastasis, we hypothesized that tumor progression induced by NONO arginine methylation was initiated by PRMT1." (PMID 33420374, 2021). "Global arginine methylation was also evaluated in tumor lysates from a cohort of animals seven days post-randomization to drug administration, which confirmed a robust increase in MMA in PRMTi- versus control-treated animals and correlated in vivo efficacy with PRMT1 target modulation." (PMID 34330913, 2021). "We have noted from our in vivo studies that PRMT1 inhibition alone may not be sufficient to completely ablate tumor formation and progression." (PMID 32415090, 2020). "In addition, PRMT1 downregulation reduced OV6+ subset-induced tumorigenicity and tumour growth." (PMID 31043582, 2019). "Thus, we believe that CDKN1A expression may be involved downstream of PRMT1 and that regulation of CDKN1A by PRMT1 plays an important factor for tumor growth and formation in HCC." (PMID 29383172, 2017). "PRMT1 may be an important co-activator of PXR in activating MDR1 gene during acquired resistance, and PRMT1 inhibitor combined with chemotherapy drugs may be a new strategy for overcoming tumor MDR." (PMID 26934120, 2016). "Notably, PRMT1 knockdown alone did not affect tumor growth in the absence of targeted drugs." (PMID 39699269, 2025). "We found that PRMT1 inhibitor treatment stimulated macrophages infiltration in only CT26-cGAS-WT cell-engrafted tumor, but not the CT26-cGAS-KO cell-engrafted tumor." (PMID 37193698, 2023). "Therefore, PRMT1 inhibitors may exert their therapeutic effects in controlling tumor migration by inhibiting the EMT process, and changes in biomarkers and/or functions related to TGF-β/SMAD-mediated EMT can reflect the responses of tumor cells to PRMT1 inhibitors to a certain extent." (PMID 35755248, 2022). "To identify the PRMT responsible for arginine methylation of NONO in CRC cells, we examined PRMT1, PRMT3, PRMT4, PRMT5, PRMT6, and PRMT8 mRNA and protein levels in paired tumor and adjacent normal tissues." (PMID 33420374, 2021). "Statistically significant differences in co-expression of PRMT1 with ZEB1, RUNX1 and TWIST1 were observed only in ccRCC, but not in other analyzed tumor types." (PMID 31655611, 2019). "Homogenous positive or homogenous negative PRMT1 and ZEB1 expression on TMA, corresponded to the same staining pattern on whole-mount section, regardless of the tumor type or nuclear grade." (PMID 31655611, 2019). "Moreover, utilizing the XCELL immune scores and the tumor immune estimation resource (TIMER) immune scores, we discovered a negative correlation between PRMT1 expression and both immune scores and immune microenvironment scores." (PMID 40927753, 2025). "Notably, PRMT1 inhibition also led to an increased population of the CD8+ PD-1+ T cells in CT26-cGAS-WT, but not the CT26-cGAS-KO cell-engrafted tumor." (PMID 37193698, 2023). "Moreover, PRMT1 inhibition increased the CD80 MFI in macrophages, indicating a relatively higher level of CD80 activation and cytotoxic T cells (GranB+CD8+) in CT26-cGAS-WT, but not the CT26-cGAS-KO cell-engrafted tumor." (PMID 37193698, 2023).
tumor (continued). "Notably, PRMT1 inhibition alone restricted neither tumor growth nor overall survival of CT26 or MC38, while the combination of PRMT1 inhibition and anti-PD-1 antibody substantially slowed tumor growth and increased the survival rate in both CT26 and MC38 tumor-engrafted mouse models." (PMID 37193698, 2023).
infection (16 papers, 2016 to 2025). The state of being infected such as from the introduction of a foreign agent such as serum, vaccine, antigenic substance or organism. "Taken together, this suggests that while cells with reduced PRMT1 are still susceptible to infection (and thus are initially resistant to G418) the viral genomes were lost as the cells divided resulting in non-amplifying colonies." (PMID 39386465, 2024). "We observed a deficit of plasma cells and GC B cells in mice containing Prmt1-deficient B cells following either immunization with a protein antigen in adjuvant or infection with influenza virus." (PMID 29026071, 2017). "Consequently, PRMT1 deficiency drives macrophages toward a proinflammatory M1 phenotype, exacerbating inflammatory damage and mortality during infection." (PMID 41256732, 2025). "Inhibition of PRMT1 impacts the ability of HPV18 genomes to establish a long-term infection in primary cells." (PMID 39386465, 2024). "In this paper, we focused on how PRMT1 impacts the infection, establishment and persistence phase of the viral lifecycle." (PMID 39386465, 2024). "Based on the scRNA-Seq data, HPV18(+) cells express higher levels of PRMT1 mRNA compared to mock infected cells at 10 days post infection." (PMID 39386465, 2024). "Infection of vehicle treated cells, expressing wildtype levels of PRMT1, supported robust establishment of infection, with numerous large colonies." (PMID 39386465, 2024). "To further establish a role of PRMT1 on viral transcriptional regulation following infection, we generated primary human cervical keratinocytes expressing a doxycycline inducible shRNA targeting PRMT1." (PMID 39386465, 2024). "Cells were treated with doxycycline to induce the expression of PRMT1 shRNA 3 days before infection and maintained shRNA mediated knockdown for a total of 10 days (i.e., seven days post infection)." (PMID 39386465, 2024). "In this study we show that HPV upregulates the expression of PRMT1 mRNA, protein, and enzymatic activity at every stage of the viral lifecycle: from infection, to productive replication, and during oncogenic progression." (PMID 39386465, 2024). "Decreased PRMT1 expression was observed in the colons of mice after the indicated lentivirus virus (LV) infection." (PMID 33853662, 2021). "We used the SK-N-SH cell line with a low MYCN level in this study and knocked down the PRMT1 expression via lentiviral shRNA infection." (PMID 30741995, 2019). "In conclusion, HPV upregulates PRMT1 shortly after infection and during persistent infection." (PMID 39386465, 2024). "PRMT1 is critical for the establishment of a persistent infection in primary cells." (PMID 39386465, 2024). "The infection and expression efficiency of PRMT1 was verified by immunoblotting." (PMID 31043582, 2019). "As was seen 10 days post-infection, HPV18 increases the steady state levels of PRMT1 in these stable cells at the mRNA and protein levels." (PMID 39386465, 2024). "When PRMT1 is knocked down, the expression of IFN -β post infection with SeV and HSV-1 is notably attenuated." (PMID 38116532, 2023). "Upon infection with SeV or HSV-1, PRMT1 forms oligomers possessing methyltransferase activity." (PMID 38116532, 2023). "Interestingly, it has been reported that the infection by EBV activates several PRMTs, including PRMT1, and inactivates PADI4, the main peptidylarginine deiminase." (PMID 36350639, 2022). "Transient infection could suppressthe PRMT1 expression, but could not induce senescent phenotypes or genes (data not shown)." (PMID 30741995, 2019).